DRD2 (dopamine receptor D2)
Diseases named in the same sentence as DRD2 in open-access papers (continued):
Sharing a sentence is not in itself a finding about the gene and the disease.
alcoholism (continued). "The reward deficiency hypothesis originated from genetic data showing that a variant in the dopamine D2 receptor gene (Taq1A DRD2) was more prevalent in patients with alcohol dependence and was associated with a hypo-dopaminergic state." (PMID 24179792, 2013). "In addition to past associations with ND, ANKK1 and DRD2 have been associated with other neurobehavioral traits including alcohol dependence, reinforcement learning, working memory, and executive function." (PMID 23691092, 2013). "In this review, we discuss some of the evidence suggesting that alternative splicing of candidate genes such as DRD2 (encoding dopamine D2 receptor) may form the basis of the mechanisms underlying the pathophysiology of alcoholism." (PMID 20617039, 2010). "Therefore, we investigated the association of three single nucleotide polymorphisms (SNP) in DRD2 gene with alcohol dependence in the north Indian subjects." (PMID 20146828, 2010). "Although the DRD2 TaqI A polymorphism and alcohol dependence have been studied extensively, it emerged that this polymorphism may affect substrate-binding specificity." (PMID 20146828, 2010). "Since 1990, many studies have addressed possible association of DRD2 polymorphism with alcoholism." (PMID 20146828, 2010). "Moreover, numerous association studies have specifically implicated the DRD2 gene in the development of alcohol dependence as well as in smoking." (PMID 15986718, 2000). "Moreover, polymorphisms of the DRD2 gene are linked with an altered risk of alcoholism." (PMID 20617039, 2010). "Also, in a recent association study, COGA researchers have found that alcoholism association with the DRD2 region actually may be the result of an association with the nearby ankyrin repeat and kinase domain containing 1 (ANKK1) gene." (PMID 23584748, 2008). "At least one subtype of severe alcoholism appears to be influenced by the polymorphic pattern of the DRD2 gene and the differential expression of its receptors." (PMID 38765881, 2024). "The Neurogeneticist Kenneth Blum, Ph.D., DHL, with Dr. Ernest Noble of UCLA, published the first study to associate an allele of the D2-dopamine receptor gene (DRD2) and severe alcoholism in JAMA in 1990." (PMID 39618491, 2024). "We observed the activation of the Drd1 and Drd2 genes, coding for dopamine receptor 1 and 2 of the dopaminergic synapse, which are also key elements of the cocaine addiction- and alcoholism-related pathways." (PMID 36981011, 2023). "The first ever confirmed psychiatric genetic discovery by the Blum and Noble’s group, the association of the Dopamine D2 Receptor (DRD2) gene and severe alcoholism, was published in JAMA in 1990." (PMID 30197787, 2017). "The results of previous studies addressing the role of the dopaminergic system in the development of alcohol dependence suggest that the dopamine receptor DRD2 gene is a potential candidate gene involved in such a common etiopathogenic pathway." (PMID 25415204, 2014). "They found that the genetic variant of the DRD2 gene associated with the anxiety, depression (ANX/DEP) alcoholic phenotype, and the genetic variant of the MAOA gene was associated with alcoholism." (PMID 24878765, 2014). "They concluded that though the -141delC variant of DRD2 might be a protective factor against the development of withdrawal symptoms, it might also be a risk factor in a highly burdened subgroup of alcoholics with a paternal and grand-paternal history of alcoholism." (PMID 20146828, 2010). "Of the five dopamine receptor subtypes, the D2 receptor subtype (DRD2) has been extensively studied in alcoholism." (PMID 20617039, 2010). "The minor (A1) allele of DRD2 and major (G1) allele of GABA receptor beta 3 (GABRB3), however, have been associated with alcoholism risk independently and in combination in a study of severely alcoholic and nonalcoholic Caucasians." (PMID 23584748, 2008).
alcoholism (continued). "One example of how genetic discovery in human alcoholics can be translated to animal research involves the dopamine D2 receptor gene (called DRD2 in humans and Drd2 in mice)." (PMID 12875048, 2002). "The findings revealed that the presence of the A1 allele of the DRD2 gene accurately classified 77% of the individuals with alcoholism, while its absence correctly classified 72% of the nonalcoholics." (PMID 38766604, 2024). "Blum and Noble pointed out that the DRD2 A1 allele was not specific for alcoholism but was a reward-linked genetic polymorphism." (PMID 37560184, 2023). "The allelic association of the A1 allele of the DRD2 gene with alcohol-dependence was found in males but not in females." (PMID 36873223, 2023). "When experiencing many negative life events in the past 12 months, DRD2 Taq1 A1 allele carriers showed higher levels of alcohol dependence than non-carriers." (PMID 35328003, 2022). "We based expected effect sizes (R2) of the interaction between a DRD2 and stressful environments on the severity of alcoholism (R2 = 0.07), main effect of the DRD2 genotype on problematic gaming (R2 = 0.11), and main effect of interpersonal stressful environments on problematic gaming (R2 = 0.09)." (PMID 35328003, 2022). "The consensus of the literature unequivocally establishes the importance of the DRD2 A1 allele and other associated alleles and gene loci [ANKK1] with 601 articles listed in PUBMED related to alcoholism alone (1/10/21) with preponderance in favor of the risk association." (PMID 34770047, 2021). "First, we examined whether DRD1 and DRD2 expression is affected by alcoholism, and whether alcoholism effects may be due to neuronal proportion in the alcoholic brain." (PMID 29383684, 2018). "In humans, positron emission tomography studies have revealed decreased DRD2 availability in the striatum of alcoholics, and support a hypothesis that a high DRD2 level in the striatum is a protective factor against alcoholism." (PMID 20617039, 2010). "Although association between specific variants of the DRD2 gene and alcoholism has been noted previously, no linkage study has detected alcoholism genes in this region." (PMID 16451603, 2005). "Because of its central role in the neuromodulation of appetitive behaviors, the DRD2 gene has been scrutinized as having a possible role in susceptibility to alcoholism, with mostly negative results." (PMID 14975174, 2003). "Importantly, Blum and Noble characterized the DRD2 Taq A1 allele not as specific to alcoholism but as a generalized reward gene." (PMID 38766604, 2024). "Importantly, we are the first to report SNPs associated with unequal age-of-onset distributions for susceptible cases to alcoholism [rs172677 on GRIN2B (p = 0.013), rs1439047 on NTRK2 (p = 0.005), rs63319 on ALDH1A1 (p = 0.033), and rs1079597 on DRD2 (p = 0.028)]." (PMID 28512340, 2017). "Another study analyzed the involvement of DRD2 and ANKK1 in 219 Caucasian families with alcoholism, using data collected as a part of the Collaborative Study on the Genetics of Alcoholism (COGA)." (PMID 32260442, 2020). "It is possible that the predictive role of DRD2 Taq1A on drinking over time in a sample of young adult social drinkers may differ to an association study examining presence vs. absence of alcohol dependence whereby heavy drinking patterns have already been established." (PMID 33364985, 2020). "Effects of alcoholism on the whole tissue levels of PDYN, OPRK1, DRD1, and DRD2 mRNAs in NAc were examined after adjusting for demographical data and tissue characteristics including age, PMI, brain pH, and RQI." (PMID 29383684, 2018). "The cluster of DRD2 and GRIN2B share the alcoholism pathway with NTRK2 (rs1439047) and have the same pathways of neuroactive ligand–receptor interaction and dopaminergic synapse as does DRD3 (rs2134655)." (PMID 28512340, 2017).
alcoholism (continued). "Several genotyping studies have targeted alcohol dependence in Mexican Americans, focusing on the genes involved in alcohol metabolism (ADH, ALDH, and CYP2E1), and a subset of neurotransmitter-related genes (DRD2, 5-HTTLPR, and GABRβ3)." (PMID 25527893, 2014). "Regarding DRD2 C957T, there is no study on problematic gaming, but there are several studies that have reported the DRD2 C957T gene as a candidate gene for alcohol dependence." (PMID 35328003, 2022). "In fact other work from National Institute of Alcohol Abuse & Alcoholism (NIAAA) has clearly shown significant linkage disequilibrium between the - 141 Indel and two exon seven SNPs (939Y and 957Y) of the DRD2 gene was observed over a distance of >50 kbp in the AN probands but not in the controls." (PMID 25278909, 2014). "Similarly, when experiencing higher levels of occupational or economic stress, DRD2 Taq1 A1A1 carriers showed higher alcoholism scores than non-carriers." (PMID 35328003, 2022). "Importantly, observed downregulation of DRD1 expression but unaltered KOR and DRD2 mRNA in alcoholics corroborates our previously demonstrated decline in D1-receptor as well as unchanged D2- and KOR receptor-binding potential in NAc of human alcoholics and in rat model of alcohol dependence." (PMID 29383684, 2018). "In addition, Gejman and colleagues (1994) examined the DNA sequence of DRD2 from large samples of alcoholics and schizophrenics and detected no variation in the coding segment of the gene that could account for an association with alcoholism." (PMID 31798095, 1995).
hyperprolactinemia (55 papers, 2007 to 2026). Abnormally high level of prolactin in the blood. "DRD2 deficiencies are characterized by chronic hyperprolactinemia, pituitary lactotroph hyperplasia, and prolactinomas in mice, but the role of intratumoral microbiome in prolactinomas is not known." (PMID 41655211, 2026). "EPS are caused by blockade of DRD2 in the nigrostriatal pathway, while hyperprolactinemia is caused by blockage of DRD2 in the tuberoinfundibular pathway." (PMID 40863247, 2025). "An earlier study from this group revealed that the Dopamine receptor D2 (DRD2) Taq1A A2A2 polymorphism was important in hyperprolactinemia following Risperidone treatment." (PMID 41009999, 2025). "Relating to adverse events, polymorphisms in DRD2 have been associated with antipsychotic-related hyperprolactinemia or weight gain." (PMID 36983567, 2023). "Lately, a significant association between DRD2 genetic polymorphisms and hyperprolactinemia has been established in children with ASD." (PMID 38375208, 2023). "Strong associations of some pharmacokinetic/pharmacodynamic gene variants, e.g., CYP2D6 and DRD2, with risperidone-induced hyperprolactinemia have been found in children with ASD, but such strong genetic associations have not been found directly for aripiprazole in ASD." (PMID 38375208, 2023). "Strong associations of some pharmacokinetic/pharmacodynamic gene variants, e.g., CYP2D6 and DRD2, with risperidone-induced hyperprolactinemia have been found in children with ASD, but such genetic associations have not been found directly for aripiprazole in ASD." (PMID 38375208, 2023). "For example, DRD2 may influence the susceptibility to hyperprolactinemia associated with OLZ treatment." (PMID 36313772, 2022). "Although there is not much research investigating the role of genetic variance on antipsychotic-induced hyperprolactinemia, any DRD2 polymorphism that increases the risk for EPS will also increase the risk for hyperprolactinemia, as both adverse effects are mediated by D2R blockade." (PMID 34209185, 2021). "We used LacDrd2KO females with lifelong severe hyperprolactinemia due dopamine-D2 receptor deletion from lactotropes, and slow onset of metabolic disturbances, and compared them to their respective controls (Drd2 loxP/loxP)." (PMID 35757410, 2022). "Data obtained with lymphoblastoid cell lines suggested that -241G carriers have higher DRD2 expression levels than non-carriers, which is consistent with our conclusion that DRD2 -241A>G is involved in hyperprolactinemia." (PMID 34690776, 2021). "Female Drd2−/− mice have pituitary hyperplasia, chronic hyperprolactinemia, and provide an experimental model for dopamine agonist resistant prolactinomas." (PMID 25505910, 2014). "D2R knockout (Drd2−/−) mice generated by targeted mutagenesis and lacDrd2KO mice, generated by Cre LoxP technology, have chronic hyperprolactinemia, pituitary hyperplasia, and provide experimental models for dopamine agonist resistant prolactinomas." (PMID 25505910, 2014). "The DRD2 gene (rs1799978, TT) is correlated with good response to risperidone treatment; and the ANKK1/DRD2 (rs1800497, GG) is correlated with reduced risk for hyperprolactinemia and weight gain but increased possibility for tardive dyskinesia." (PMID 33858454, 2021). "Whether DRD2 rs1800497 controls bone density through elevated prolactin level or other mechanisms unrelated to hyperprolactinemia requires further investigation." (PMID 32764574, 2020). "Additionally, these results are difficult to compare with our own in vitro findings since the Drd2-/- KO animals displayed chronic hyperprolactinemia, whose main pancreatic effect is to increase the proliferation of beta cells." (PMID 25886074, 2015). "In addition, DRD2 agonists improve glucose and lipid metabolism in patients with hyperprolactinemia and acromegaly." (PMID 21603181, 2011).
hyperprolactinemia (continued). "In the past two decades, DRD2 agonists such as CAB and bromocriptine (BRC) have been the first-choice treatment for controlling hyperprolactinemia and shrinking the volume of prolactinomas." (PMID 34221237, 2021).
Cognitive impairment (37 papers, 2013 to 2025). Abnormal cognition is characterized by deficits in thinking, reasoning, or remembering. "Our work indicates that the potential targeting of the Drd2-associated mPFC-BLA neural circuit may serve as a therapeutic strategy in alleviating the cognitive deficits that commonly occur in sleep disorder patients." (PMID 40963920, 2025). "Methylation of the promoter of dopamine receptor genes (DRD2, DRD3, and DRD4) also alters dopamine expression and causes cognitive deficits associated with SCZ." (PMID 36406755, 2022). "In accordance with our results, it has been reported that DRD1, DRD2, DRD3, DRD4, and SLC2A9 are associated with cognitive performance or cognitive impairment." (PMID 34285142, 2021). "Taken together, our data was in accordance with a recent animal study which showed that altered DRD2 expression correlated with selective cognitive impairments in working memory and behavioral flexibility." (PMID 25178928, 2014). "Our work may highlight the potential of targeting Drd2 signaling in the mPFC with its antagonist per se for attenuating cognitive deficits commonly experienced in patients with sleep disorders." (PMID 40963920, 2025). "Our data further demonstrated that Drd2-mediated-CaMKIIα+ neuronal inhibition did not participate in sleep regulation but contributed to CSD-induced cognitive impairment." (PMID 40963920, 2025).
Dyskinesia (31 papers, 2011 to 2025). A movement disorder which consists of effects including diminished voluntary movements and the presence of involuntary movements. "For instance, among ADR studies, CAn STR 13, 14 (DRD2) was found to be most significantly associated with dyskinesia, rs1801133 (MTHFR) with hyper-homocysteinemia, and rs474559 (HOMER1) with hallucination." (PMID 28927418, 2017). "With 13, 14 CAn STR repeats in DRD2 gene being the most significant variant associated with dyskinesia, followed by rs1801133 (MTHFR) associated with hyper-homocysteinemia, rs474559 (HOMER1) with hallucinations." (PMID 28927418, 2017). "Interestingly, both studies that show reduced dyskinesias were conducted in the Italian population with the polymorphism DRD2 CAn-STR." (PMID 34281267, 2021). "DRD2 rs1799732 has already been associated with the occurrence of dyskinesia." (PMID 31156712, 2019). "From 37 candidate studies on levodopa toxicity, 18 genes were found associated, of which, CAn STR 13, 14 (DRD2) was most significantly associated with dyskinesia, followed by rs1801133 (MTHFR) with hyper-homocysteinemia, and rs474559 (HOMER1) with hallucination." (PMID 28927418, 2017). "The effect of Dopamine receptor 2 (DRD2) SNP’s on dyskinesia is a point of contention in current literature, as some studies indicate an increased risk of developing dyskinesia, while others revealed a protective effect on the incidence of dyskinesia." (PMID 34281267, 2021). "We report the associations of DRD2 rs1799732, NRG1 rs3735781, CAT rs1001179, SOD2 rs4880, and SLC22A1 rs628031 with time to occurrence of dyskinesia under the univariate analysis." (PMID 31156712, 2019). "Among South Asian (SAS) population, Israelis were most abundantly studied representing association of rs393795 (DAT1), rs886292 (ABCC8), rs11880894 (RYR1) and rs1800497 (DRD2) with dyskinesia." (PMID 28927418, 2017). "Other polymorphisms including rs886292 (ABCC8), rs11880894 (RYR1), rs1800497 (DRD2), rs6265 (BDNF), rs11646587, rs7192557 and rs8057394 (GRIN2A) were found to be associated with dyskinesia in patients administered with levodopa medication." (PMID 28927418, 2017). "DRD2 is related to peak-dose dyskinesias induced by levodopa in patients with PD." (PMID 37089789, 2023). "For example, some investigations into genetic variants of the dopamine receptor D2 (DRD2) gene reported an association with dyskinesia, whereas others did not identify an association between DRD2 genotypes and the risk for dyskinesia." (PMID 35096365, 2022). "We did not confirm the association between DRD2 rs1799732 and dyskinesia and DRD2 rs1799732 and nausea/vomiting reported in Brazilian patients." (PMID 30745869, 2019). "Finally, dopamine receptor D2 gene polymorphisms were shown to provide a strong protection toward dyskinesia only in men and not in women." (PMID 40439072, 2025). "Carriers of dopamine receptors DRD2 haplotypes and possibly the BDNF variants rs6265 and DRD3 haplotypes, were at increased risk of dyskinesia, suggesting that these genes may be involved in dyskinesia-related pathomechanisms." (PMID 35743271, 2022). "Interestingly, TrkB cell surface reduction did not affect TrkB phosphorylation levels after long-term treatment with a DRD2 agonist, which might explain why previous studies have reported that high doses of levodopa that induced dyskinesia rescue spine morphology in iSPNs." (PMID 37887070, 2023). "In another study, the carriers of dopamine receptor DRD2 and DRD3 haplotypes, as well as the BDNF variant rs6265, were associated with an increased risk of dyskinesia, suggesting that these genes may be implicated in dyskinesia-related pathomechanisms in Parkinson’s disease patients." (PMID 35743271, 2022). "Dopamine receptor D2 (DRD2), a dopaminergic receptor subtype, polymorphisms protect L-Dopa induced dyskinesias in men but do not has protective effects for women." (PMID 30621042, 2019).